NCAPD3 (non-SMC condensin II complex subunit D3)
Diseases named in the same sentence as NCAPD3 in open-access papers (continued):
Sharing a sentence is not in itself a finding about the gene and the disease.
pancreatic cancer (1 paper, 2024). "While in pancreatic cancer, NCAPD3 serves as a predictive indicator for clinical trials." (PMID 39944401, 2024).
round cell liposarcoma (1 paper, 2023). A poorly differentiated liposarcoma, characterized by the presence of solid sheets of primitive round mesenchymal cells and the absence of myxoid stroma. "NCAPD3 was upregulated in Round Cell Liposarcoma with a fold change of 2.213 (p = 0.003)." (PMID 37192046, 2023).
sarcoma (1 paper, 2023). A usually aggressive malignant neoplasm of the soft tissue or bone. "From our research results, we also found that high expression of NCAPD3 was related to the poor prognosis of sarcoma in the Kaplan-Meier Plotter database." (PMID 37192046, 2023). "In the Kaplan-Meier Plotter database, high expression of NCAPD2, NCAPG, NCAPH, and NCAPD3 was correlated with poor overall survival in sarcoma patients (p < 0.05), HR = 2.23 (p = 0.00016), 1.63 (p = 0.015), 1.83 (p = 0.0025), and 1.63 (p = 0.024), respectively." (PMID 37192046, 2023). "Six members of the NCAPs family, including NCAPD2, NCAPG, NCAPH, NCAPD3, NCAPG2, and NCAPH2, have been found in different types of sarcomas." (PMID 37192046, 2023). "The high expression of NCAPD2, NCAPG, NCAPH, NCAPD3, and NCAPH2 were all correlated with the relapse-free survival of sarcoma patients, HR = 2.76 (p = 3.3e-05), 2.72 (p = 0.0012), 2.71 (p = 0.0026), 1.87 (p = 0.01) and 2.08 (p = 0.029) respectively." (PMID 37192046, 2023). "In this study, ONCOMINE, GEPIA, Kaplan-Meier plotter, DAVID (KEGG and GO analysis), and TIMER datasets were utilized to study the high expression, prognosis analysis, signal pathway and immune correlation of NCAPD2, NCAPG, NCAPH, NCAPD3, NCAPG2, and NCAPH2 in sarcoma for the first time." (PMID 37192046, 2023). "Up to now, NCAPD2, NCAPG, NCAPH, NCAPD3, NCAPG2, and NCAPH2 have not been mentioned in sarcoma, except NCAPG mentioned in Ewing sarcoma." (PMID 37192046, 2023). "NCAPD3 and NCAPH2 were also upregulated in sarcoma samples but with no significance." (PMID 37192046, 2023).
thyroid neoplasms (1 paper, 2025). "Finaly, we did not investigate the relationship between NCAPD3 expression and the genetic characteristics of thyroid neoplasms." (PMID 40445456, 2025).
tumor (15 papers, 2011 to 2025). "To summarise, elevated mRNA levels of NCAPD3 may be associated with aggressive primary PCa tumours." (PMID 40219635, 2025). "In human prostate cell lines, NCAPD3 was also higher in all tumor cell lines (PC‐3, DU145, 22Rv1, and LNCaP) than in non‐cancer cell lines (WPMY‐1 and BPH‐1)." (PMID 39917394, 2025). "In NSCLC, upregulation of NCAPD3 promotes tumor growth via the MEK/ERK/LDHA signaling axis, with histone lactylation enhancing NCAPD3 expression and amplifying glycolysis and malignant phenotypes." (PMID 41373440, 2025). "Further investigation identified a significant correlation between NCAPD3 expression and key clinicopathological features, including tumor size and lymphovascular invasion." (PMID 40445456, 2025). "qRT-PCR analysis of twenty paired PCa tissues displayed that NCAPD3 was similarly upregulated in tumor tissues." (PMID 38561330, 2024). "NCAPD3 overexpression also accelerated tumor growth in the xenograft mouse model and repressed miR-30-5p." (PMID 38561330, 2024). "Although little is known about the expression and role of NCAPD3 in human tumors, aberrant NCAPD3 expression and its potential effects have been observed in tumor tissues." (PMID 38711992, 2024). "In conclusion, we found NCAPD3 inhibited miR-30a-5p expression to promote cell proliferation and migration and accelerate tumor growth through MALAT1 as a sponge and MYC transcriptional repression pathways." (PMID 38561330, 2024). "Our findings demonstrated that NCAPD3 gene suppressed tumor cell apoptosis through up-regulation anti-apoptotic protein Bcl-2, while down-regulating pro-apoptotic proteins including caspase-8 and Bax, ultimately inactivating the apoptotic cascade in tumors." (PMID 38566039, 2024). "RNA-seq was carried out with human CRC tissues and their corresponding normal tissues, and data analysis revealed that expression of NCAPD3 was significantly higher in tumor tissues by compared to their normal counterparts." (PMID 35689245, 2022). "Based on the key role of aerobic glycolysis in regulating tumor growth and metastasis, we speculate that NCAPD3 may involve in the proliferation and metastasis of PTCby regulating the aerobic glycolysis pathway." (PMID 40445456, 2025). "In addition, molecular network regulatory maps showed that apoptosis pathway-related genes (e.g., IRF7 and DDIT3) in tumor cells showed overall activation after NCAPD3 inhibition." (PMID 38711992, 2024). "Furthermore, we explored the expression level of NCAPD3 across different tumor stages for LUAD and LUSC patients." (PMID 38566039, 2024). "In colorectal cancer, NCAPD3 promotes tumor progression by enhancing the Warburg effect." (PMID 38566039, 2024). "Finally, a recent HotNet2 Pan-Cancer analysis suggested that multiple cancers harbor rare mutations in SMC2, SMC4, NCAPD2, NCAPD3, NCAPH2 and NCAPG2, supporting a tumor-suppressor role for condensin proteins." (PMID 36169232, 2022). "In addition, in vivo data also demonstrated that overexpression of NCAPD3 in HCT116 cells promoted tumor lung metastasis." (PMID 35689245, 2022). "However, it remained unclear whether there were miRNAs in the downstream regulation of tumor-promoting signaling of NCAPD3-mediated MALAT1 and TFs in PCa." (PMID 38561330, 2024). "Additionally, we also examined the expression of NCAPD3 in the UALCAN online tumor database." (PMID 38566039, 2024). "NCAPD3 was highly expressed in PTC tissues, and correlated with aggressive features (tumor size and lymphovascular invasion)." (PMID 40445456, 2025). "Then, we compared the expression between JAK2 and NCAPD3 or STAT3 in GTEx normal tissues and TCGA tumor tissues, and found both NCAPD3 and STAT3 showed strong positive correlations with JAK2 in tumor tissues." (PMID 39917394, 2025).
tumor (continued). "NCAPD3 was highly expressed in PTC tissues and correlated with aggressive clinicopathological features (e.g., tumor size and lymphovascular invasion), and NCAPD3 silencing inhibited proliferation, migration, invasion, and aerobic glycolysis of PTC cells." (PMID 40445456, 2025). "All tumor cells exhibited a significant decrease in miR-30a-5p expression compared to non-tumor cell lines WPMY-1 and BPH-1, especially LNCAP and 22Rv1, which was exactly contrary to NCAPD3 expression in cells." (PMID 38561330, 2024). "We have previously found that NCAPD3 was highly expressed in PCa and CRC to promote tumor progression through STAT3 upregulation of MALAT1." (PMID 38561330, 2024). "Apart from NCAPD3 regulation of STAT3, we also reported before that NCAPD3 upregulated other TFs like MYC and EZH2 to promote tumor progression." (PMID 38561330, 2024). "Results showed that the tumor weight in the NCAPD3 knockdown group was significantly lower than the negative control group (p < 0.05)." (PMID 38711992, 2024). "Therefore, the present study suggests that NCAPD3-knockdown-induced differentially expressed genes (DEGs) such as CRNDE, EDN1, and JUNB can regulate cell and tumor invasion through EGFR and PLAUR." (PMID 38711992, 2024). "Further analyses revealed a positive correlation between the NCAPD3 staining and tumor-node-metastasis (TNM) stage and grade (p < 0.05), but not with age, gender, and histology (p > 0.05)." (PMID 38566039, 2024). "Herein, we confirmed the transcription levels of non-SMC subunit NCAPD3, NCAPH2, and NCAPD2 exhibited an increase in tumor tissues compared to adjacent nontumor tissues by RNA-seq analysis, among which only NCAPD3 showed a statistically significant change." (PMID 38561330, 2024). "In order to further study the effector molecular mechanisms, the NCAPD3 knockdown differentially expressed gene data in this study were combined with literature data, and IPA was employed to construct a molecular regulatory network map of tumor cell proliferation and apoptosis." (PMID 38711992, 2024). "On the other hand, NCAPD3 increased the expression of transcription factor MYC, which directly inhibited miR-30a-5p transcription via binding its host gene LINC00472 promoter region, both of which promoted cell proliferation and migration and accelerated tumor growth in PCa." (PMID 38561330, 2024).
cancer (12 papers, 2017 to 2025). A tumor composed of atypical neoplastic, often pleomorphic cells that invade other tissues. "Notably, elevated levels and frequently mutations of NCAPD3 are found in many somatic cancers." (PMID 35689245, 2022). "Recently, the important functions of NCAPD3 in diseases, especially in cancers, have gradually attracted the attention of researchers." (PMID 39917394, 2025). "Protein expression analysis using UALCAN (University of Alabama at Birmingham Cancer data analysis portal) revealed significant differences in all subunits except NCAPD3." (PMID 41319185, 2025). "Accumulating evidence indicates that aberrant non-SMC condensin II complex subunit D3 (NCAPD3) is associated with carcinogenesis of various cancers." (PMID 38566039, 2024). "In addition to its functions in chromosome condensation and segregation, recent research has revealed that NCAPD3 is involved in the regulation of cancer progression." (PMID 38566039, 2024). "Notably, elevated levels of NCAPD3 are found in many somatic cancers." (PMID 35689245, 2022). "Using publicly available patient derived datasets obtained from TCGA, we determined that all eight condensin genes (SMC2, SMC4, NCAPD2, NCAPD3, NCAPG, NCAPG2, NCAPH, and NCAPH2) are frequently altered in at least 12 common cancer types." (PMID 31357676, 2019).
bacterial infection (2 papers, 2019). "While NCAPD3 has a known role in the regulation of innate immune responses to bacterial infection, it has yet to be linked to either Ca2+ signaling or mitochondrial division." (PMID 31653782, 2019).
colorectal (1 paper, 2022). "In vitro and in vivo experiments clearly demonstrated that NCAPD3 promoted colorectal tumorigenesis, CRC cell proliferation, migration and metastasis, suggesting that NCAPD3 was an oncogene and played a carcinogenic potential role in CRC." (PMID 35689245, 2022).
NCAPD3 also shares sentences with these, for which no sentence is quoted: non-small cell lung carcinoma (2 papers); prostate tumor (2); cardiovascular disorder (1); colitis (1); infection (1); inflammatory bowel disease (1); laminopathies (1); lung adenocarcinoma (1); lung squamous cell carcinoma (1); lymphocytic thyroiditis (1); papillary thyroid carcinoma (1); Parkinson disease (1).